KLK7 (kallikrein related peptidase 7)
Description:
May catalyze the degradation of intercellular cohesive structures in the cornified layer of the skin in the continuous shedding of cells from the skin surface. Specific for amino acid residues with aromatic side chains in the P1 position. Cleaves insulin A chain at '14-Tyr-|-Gln-15' and insulin B chain at '6-Leu-|-Cys-7', '16-Tyr-|-Leu-17', '25-Phe-|-Tyr-26' and '26-Tyr-|-Thr-27'. Could play a role in the activation of precursors to inflammatory cytokines.
Synonyms: hK7; PRSS6; SCCE
Tractability: Small molecule: a structure with a bound ligand is known; a high-quality ligand is known. Antibody: UniProt places it where antibodies can reach, with high confidence; its Gene Ontology location is reachable by antibodies, with high confidence; UniProt predicts a signal peptide or a membrane-spanning region; the Human Protein Atlas places it where antibodies can reach. PROTAC: a small molecule that binds it is known.
Target class: Serine protease; Enzyme; Serine protease PA clan; Serine protease S1A subfamily; Protease
Gene: Protein-coding gene on chromosome 19 (50,976,468 to 50,984,099, reverse strand). Ensembl gene ENSG00000169035.
Subcellular location: Secreted
Subcellular location (Human Protein Atlas): Plasma membrane; Nuclear membrane; Predicted to be secreted
Pathways (Reactome):
Developmental Biology: Differentiation of Keratinocytes in Interfollicular Epidermis in Mammalian Skin
Extracellular matrix organization: Degradation of the extracellular matrix
Gene Ontology:
Molecular function: peptidase activity; metalloendopeptidase activity; serine-type endopeptidase activity; serine-type peptidase activity
Biological process: antibacterial peptide biosynthetic process; epidermis development; extracellular matrix disassembly; protein maturation; proteolysis
Cellular component: epidermal lamellar body; extracellular region; plasma membrane; secretory granule; cornified envelope
Genetic constraint (gnomAD): Loss-of-function variants: 17 observed, 20.15 expected, observed/expected ratio (o/e) 0.84, 90% interval 0.58 to 1.26. The upper end of that interval is the gene's LOEUF score, 1.26, which puts it in group 5 of 6, group 1 being the genes least tolerant of losing a copy. Missense variants: 330 observed, 317.77 expected, observed/expected ratio (o/e) 1.04, 90% interval 0.95 to 1.14. Synonymous variants: 151 observed, 136.26 expected, observed/expected ratio (o/e) 1.11, 90% interval 0.97 to 1.27.
Homologues: Orthologues: chimpanzee KLK7 (99% identical), dog KLK7 (83% identical), pig KLK7 (81% identical), rabbit KLK7 (81% identical), macaque KLK8 (77% identical), rat Klk7 (74% identical), mouse Klk7 (73% identical), guinea pig KLK7 (69% identical), tropical clawed frog klk1 (40% identical), Drosophila melanogaster CG32808 (30% identical), Drosophila melanogaster Send2 (28% identical), Drosophila melanogaster Phae2 (26% identical), and 8 more. Paralogues in human: KLK5 (46% identical), KLK8 (45% identical), KLK4 (44% identical), KLK12 (44% identical), KLK14 (43% identical), KLK2 (42% identical), KLK1 (42% identical), KLK11 (41% identical), KLK3 (40% identical), TMPRSS4 (31% identical), PRSS58 (27% identical), PRSS54 (22% identical).
Diseases named in the same sentence as KLK7 in open-access papers:
KLK7 is named in the same sentence as 103 diseases in open-access papers, as found by Europe PMC text mining. Sharing a sentence is not in itself a finding about the gene and the disease. The quoted sentences say what the papers report.
ovarian carcinoma (21 papers, 2002 to 2025). A malignant neoplasm originating from the surface ovarian epithelium. "Although some other studies have indicated that different members of KLK family associated with specific cancers and KLK7 as preferred targets for inhibition of ovarian cancer, the distinct role of KLK7 remains to be elucidated." (PMID 33336051, 2020). "In our study, Oncomine has been systematically employed to explore the association of KLK7 mRNA expression with ovarian cancer patients." (PMID 33336051, 2020). "An association of elevated KLK7 protein expression with poor patient outcome has been reported by Psyrri and co-workers in an ovarian cancer cohort encompassing 150 tumor specimens." (PMID 33087135, 2020). "In contrast to this result, our finding revealed that overexpressed KLK7 was significantly associated with worse FPS in ovarian cancer." (PMID 33336051, 2020). "On the one hand, elevated KLK7 levels were reported to be associated with poor prognosis on protein and mRNA level, whereas, on the other hand, an association of KLK7 with favorable prognosis of ovarian cancer patients has been indicated in other studies." (PMID 33087135, 2020). "Recently, we found that ovarian cancer patients with high KLK7 tumor tissue ELISA-levels had a two-fold lower risk of mortality or relapse compared with patients who displayed low levels." (PMID 25436002, 2015). "In view of recent studies showing that elevated KLK5 and KLK7 values are associated with advanced stage, higher nuclear grade and a poor prognosis in ovarian cancer patients, the clinical impact of these two additional KLKs was tested." (PMID 25436002, 2015). "The most commonly KLK7 positive cancers included squamous cell carcinomas from various sites of origin, ovarian carcinomas, pancreatic adenocarcinomas, and salivary gland tumors." (PMID 38961454, 2024). "Several studies have shown that KLK5 and KLK7 serve as serological biomarkers and indicators of poor prognosis in breast and ovarian cancer." (PMID 33588911, 2021). "By the comparison of KLK7 expression in four data sets, meta-analysis demonstrated that KLK7 was significantly increased in two types of ovarian cancer, namely, ovarian serous adenocarcinoma and ovarian endometrioid adenocarcinoma." (PMID 33336051, 2020). "It was only analyzed by online databases, and experimental or clinical validation would be needed to confirm the expression of KLK7 in ovarian cancer." (PMID 33336051, 2020). "It was found that the expression of KLK7 was higher in ovarian cancer compared with other types of cancer, such as gastric cancer and pancreatic cancer." (PMID 33336051, 2020). "Subsequently, our analysis suggested that high expression of KLK7 in ovarian cancer compared to normal controls among four data sets." (PMID 33336051, 2020). "Regarding its clinical prognostic value, KLK7 has been analyzed in various human solid tumors, including ovarian cancer." (PMID 33087135, 2020). "The prognostic strength of KLK7 mRNA expression concerning PFS was validated using the online tool Kaplan-Meier Plotter - Ovarian Cancer (HR = 1.31, p = 0.034; for details see)." (PMID 33087135, 2020). "Taken together, these studies strongly suggest that KLK7 overexpression has a tumor-supporting role and contributes to a more aggressive phenotype in ovarian cancer." (PMID 33087135, 2020). "The expression of KLK7 was found to be increased in four various ovarian cancer data sets compared with the healthy tissues." (PMID 33336051, 2020). "The expression of KLK7 in human ovarian cancer was evaluated by Oncomine and Cancer Cell Line Encyclopedia database." (PMID 33336051, 2020). "The KLK7 gene was ranked as 948.0 in all expressed genes, which means that KLK7 mRNA expression was significantly increased in two types of ovarian cancer." (PMID 33336051, 2020). "KLK7 gene should be considered as potential prognostic biomarker for a better understanding of ovarian cancer progression and therapy." (PMID 33336051, 2020).
ovarian carcinoma (continued). "Elevated levels of Kallikrein 6 and 7 (KLK6 and KLK7) was reported in sera of ovarian carcinoma subtypes, depicting their potential to improve early detection of OC." (PMID 31608277, 2019). "Overexpression of KLK6 and KLK7 mRNA was specific to ovarian cancer, in particular to serous and papillary serous subtypes." (PMID 25477184, 2014). "Two kallikrein (KLK) serine protease family members (KLK6 and KLK7) were found to be significantly overexpressed relative to normal controls in most of the ovarian cancer cell lines examined." (PMID 25477184, 2014). "We have reported that combined expression of KLK4, KLK5, KLK6, and KLK7 in OV-MZ-6 ovarian cancer cells regulates integrin expression, cell adhesion, and promotes a malignant phenotype." (PMID 27605189, 2013). "Our results showed that KLK6 and KLK7 are upregulated in ovarian cancer tissues over other cancer types." (PMID 23319948, 2012). "The significance of KLK7 in ovarian cancer early detection is directly related to its upregulated levels in ovarian cancer cells." (PMID 23319948, 2012). "For example, KLK7 positivity rates of ≥ 90% have been described for breast cancers, ovarian carcinomas, oral squamous cell carcinomas, adenocarcinomas of the colon, adenocarcinoma of the cervix, and different subtypes of renal cell carcinomas in individual studies." (PMID 38961454, 2024). "Moreover, Klk7 overexpression has been documented in various malignant tumors, including ovarian cancer, pancreatic cancer, thyroid cancer, and colon cancer." (PMID 38203721, 2023). "Additionally, KLK7 was also highly expressed in human ovarian cancer cell lines, as implicated by CCLE database, supporting the critical role of KLK7 in ovarian cancer initiation or progression." (PMID 33336051, 2020). "In ovarian cancer, KLK7 overexpression was found to induce chemoresistance to paclitaxel and increase levels of α5/β1 integrins, which may promote ovarian cancer cell dissemination." (PMID 33087135, 2020). "KLK5 and KLK7 are majorly involved in skin desquamation, a process which may be similar to the shedding of tumor cells from the primary tumor in ovarian cancer leading to intraperitoneal dissemination." (PMID 33087135, 2020). "Additionally, KLK7 was found to be related to paclitaxel chemoresistance in epithelial ovarian cancer patients." (PMID 33087135, 2020). "Moreover, CCLE database analysis revealed that the mRNA expression levels of KLK7 in ovarian cancer compared with the other cancer cells." (PMID 33336051, 2020). "Therefore, we aimed at exploring the interrelation between KLK5 and KLK7 mRNA levels as well as the clinical relevance of KLK7 expression in the same ovarian cancer patient cohort, which was previously used for KLK5 mRNA analysis." (PMID 33087135, 2020). "Besides, we observed pronounced correlations between KLK5 and KLK7 mRNA levels as well as between their antigen levels, providing good evidence for the coordinate expression of KLK5 with KLK7 in ovarian cancer." (PMID 33087135, 2020). "Knowledge of the expression of KLK7 may be useful for better understanding the outcome in ovarian cancer patients." (PMID 33336051, 2020). "Finally, the impact of KLK7 on clinical prognosis was investigated in distinct subtypes of ovarian cancer patients by UALCAN database and Kaplan–Meier plotter database." (PMID 33336051, 2020). "KLK7 is over expressed in pancreatic cancer tissues, and the expression level of KLK7 could be an important prognostic indicator in different cancers including colon cancer, ovarian cancer and pancreatic cancer." (PMID 29560118, 2018). "KLK4, KLK5, KLK6 and KLK7 have been found related to the prognosis of ovarian cancer." (PMID 27825132, 2016). "We have previously demonstrated that KLK6 and KLK7 can serve as ovarian cancer-specific biomarkers." (PMID 27036110, 2016).
ovarian carcinoma (continued). "In particular, the present study has confirmed earlier findings showing that KLK5 is associated with advanced and more aggressive disease, and that KLK7 may be a favorable prognostic marker in ovarian cancer." (PMID 25436002, 2015). "Assays based on KLK6 and KLK7 expression may provide specific and sensitive information for early detection of ovarian cancer." (PMID 25477184, 2014). "Elevated expression of KLK4, KLK5, KLK6, and KLK7 are linked to multi-cellular aggregation of ovarian cancer cells and non-responsiveness of patients to paclitaxel." (PMID 27605189, 2013). "KLK7 secreted in the ovarian cancer microenvironment could in turn accelerate cancer progression." (PMID 33336051, 2020). "However, little is known about the expression and prognostic role of KLK7 in ovarian cancer." (PMID 33336051, 2020). "In addition, we identified KLK7 as overexpressed in ovarian cancer." (PMID 14760385, 2004). "Activation of the TGFβ pathway was also observed in a proteomic analysis of the secretome of an ovarian cancer cell line engineered to overexpress KLK4, KLK5, KLK6 and KLK7." (PMID 33255452, 2020). "Prostasin (PRSS8), GSTT1, FOLR1, KLK6, KLK7, and ALDH1 are all currently under research and clinical trials and are also potential biomarkers for early detection of ovarian cancer." (PMID 23319948, 2012). "Using this approach, we have previously reported that several candidates including hepsin, stratum corneum chymotryptic enzyme (SCCE/KLK7), protease M (KLK6), TADG-12, and TADG-14 (KLK8) are abundantly expressed in ovarian cancers." (PMID 15611789, 2005). "In ovarian cancer, both KLK5 and KLK7 expression levels were previously reported to be up-regulated in ovarian neoplasms, compared to benign and/or low malignant potential carcinomas, indicating that they may represent diagnostic factors in this tumor entity." (PMID 33087135, 2020). "Studies have found that KLK7 increases the expression of integrity adhesion receptors and both forms of the produced serine proteases (KLK7 and the nonproteolytic form) work in ovarian cancer peritoneal invasion." (PMID 33336051, 2020). "Although KLK7 expression was not significantly correlated with poor OS, the higher expression of KLK7 in all patients with ovarian cancers is significantly correlated with better PFS (P < 0.05)." (PMID 33336051, 2020). "As previous studies have shown that KLK7 mediates both proteolytic and nonproteolytic functions in ovarian cancer, we used an enzymatically inactive KLK7 mutant, where the active site serine residue has been replaced by alanine." (PMID 28636767, 2017). "In fact, KLK6 and KLK7 showed almost no expression in normal samples but have previously been found to be early stage biomarkers for ovarian cancer." (PMID 29088818, 2017). "Among these, KLK6, KLK7, KLK8, and KLK10 showed the highest statistical significance in ovarian cancer effusions over other cancer groups, suggesting that these kallikreins might be useful biomarkers in differential diagnosis of ovarian cancer." (PMID 23319948, 2012). "Six kallikreins, KLK4, KLK5, KLK6, KLK7, KLK10, and KLK15, are markers of poor prognosis in ovarian cancer." (PMID 20354523, 2010). "A recent report showed a concordant higher expression of both KLK5 and KLK7 in ovarian carcinomas, especially late-stage serous carcinomas, compared with normal ovaries and benign adenomas." (PMID 20354523, 2010).
breast carcinoma (17 papers, 2004 to 2025). "KLK5 is considered the physiological activator of KLK7 and both serve as serological biomarkers, indicators of poor prognosis, and have a role in tumor invasion and angiogenesis in breast cancer." (PMID 40426890, 2025). "According to a study, the value of the kallikrein-related peptidase 5 gene KLK5 and KLK7 in the diagnosis and prognosis prediction of breast cancer patients was far from clear." (PMID 38137332, 2023). "The mRNA levels of both KLK5 and KLK7 were downregulated in breast cancers relative to normal and benign tissues, and downregulated in metastases compared to primary cancers." (PMID 38137332, 2023). "KLK7 was found to be aberrantly expressed in various cancers, such as breast cancer, lung carcinoma and colon cancer." (PMID 32076707, 2020). "The mRNA expression of KLK7 ranks fourth highest in breast cancer and this is based on Affy gene chip data." (PMID 33336051, 2020). "In breast cancer, KLK7 was significantly downregulated in the sera of breast cancer and benign breast disease patients, implying a role in the pathogenesis of infiltrating ductal carcinoma." (PMID 33336051, 2020). "When it comes to KLK7, its mRNA was significantly lower in either stage I or stage II breast cancer patients, and its high mRNA expression was related to a favorable prognosis." (PMID 33150763, 2020). "KLK5, for instance, was reported to be downregulated in breast cancer, whereas elevated expression of KLK6, KLK7 and KLK10 has been associated with multiple cancers and poor prognosis in gastric and colorectal cancer." (PMID 29263803, 2016). "Conversely, in prostate cancer and breast cancer, the expression of Klk7 is downregulated." (PMID 38203721, 2023). "Furthermore, KLK5 and KLK7 are co-expressed in different cancer types such as breast cancer or oral squamous cell carcinoma." (PMID 33087135, 2020). "Our lab has shown in the past that KLK7 may serve as a potential biomarker for breast cancer patients and that its overexpression in intracranial tumours reveals a less favourable outcome." (PMID 19367279, 2009). "However, contradictory findings have already been reported for KLK7 in breast cancer." (PMID 25436002, 2015). "Our PCA analysis suggests that SOD2, KLK5, KLK7, and IL8 play a significant role in the worsening of breast cancer pathology." (PMID 40426890, 2025). "Like PROM1 and KLK7, NDRG1 is most highly expressed in basal breast cancers; yet, when expressed in ER-positive primary tumors, NDRG1 confers significantly worse disease-specific survival outcomes." (PMID 33407744, 2021). "An analysis of tumors with the most recurrent outlier loss, ESR1, revealed concurrent upregulation of genes typically expressed in basal breast cancers, such as PROM1, KLK7, and NDRG1, suggesting a selection of a more basal-like phenotype in endocrine-resistant disease." (PMID 33407744, 2021). "The general lack of detectable KLK7 expression fits well to earlier studies reporting downregulation of KLK7 mRNA in breast cancers, but there are also studies suggesting that KLK7 can be upregulated specifically in hormone receptor negative and triple negative breast cancers." (PMID 38961454, 2024).